PLTP (phospholipid transfer protein)
Diseases named in the same sentence as PLTP in open-access papers (continued):
Sharing a sentence is not in itself a finding about the gene and the disease.
Insulin resistance (6 papers, 2009 to 2022). Increased resistance towards insulin, that is, diminished effectiveness of insulin in reducing blood glucose levels. "In agreement with our findings, reported that a higher PLTP activity was related to insulin resistance in humans." (PMID 26034989, 2015). "On the other hand, some key enzymes involved in HDL metabolism, such as CETP, LCAT, hepatic lipase(HL) and protein phospholipid transfer protein(PLTP), are changed in obese people with insulin resistance, promoting this process." (PMID 21988829, 2011). "In addition, the absence of PLTP is also associated with an increase in the ceramide levels, which are known to be closely related to the pathogenesis of insulin resistance." (PMID 36362012, 2022). "APOA1 and PLTP are members of the PPAR signaling pathway and are closely related to insulin resistance, and glucose and lipid metabolism, and participate in the regulation of thermogenesis." (PMID 36292795, 2022).
type 2 diabetes (6 papers, 2008 to 2022). "Increased PLTP mass and PLTP activity have also been reported in patients with type 2 diabetes, and this is associated with increased intima–media thickness." (PMID 25725623, 2015). "Furthermore, an association between PLTP activity and inflammatory marker CRP was found in patients with CVD and type 2 diabetes." (PMID 29565987, 2018). "ApoM promotes the formation of pre–β-HDL from α-HDL, and lower levels of ApoM may explain why pre-β-HDL formation is not increased in type 2 diabetes, despite increased PLTP activity." (PMID 25725623, 2015).
hypertriglyceridemia (4 papers, 2014 to 2024). A laboratory test result indicating elevated triglyceride concentration in the blood. "At present, it is unclear why C3H-S mice with low PLTP expression and activity exhibit overt hypertriglyceridemia." (PMID 37620514, 2023). "Previous studies have demonstrated that LXRα directly upregulates the expression of genes involved in fatty acid synthesis, such as FASN and PLTP, thereby influencing intracellular de novo synthesis of fatty acids and ultimately leading to hypertriglyceridemia." (PMID 39564113, 2024). "Elevated serum PLTP levels in cancer patients following treatment with topoisomerase I inhibitors may serve as a biomarker for tracking the progression of hypertriglyceridemia." (PMID 38022651, 2023).
type 1 diabetes (4 papers, 2008 to 2014). "It has been indicated that patients with type 1 diabetes have greatly increased phospholipid transfer protein (PLTP) activity, and higher PLTP activity was associated with more circulating apoA-I levels." (PMID 24593955, 2014). "The activities of the HDL-associated enzymes PLTP (p < 0.001), and CETP (p = 0.007) were higher and paraoxonase (PON-1) activity, an anti-oxidative enzyme bound to HDL, decreased in patients with type 1 diabetes (p = 0.027)." (PMID 24959195, 2014). "These authors had previously demonstrated that patients with type 1 diabetes have a significantly elevated PLTP activity and that this activity is correlated with HDL levels." (PMID 19627602, 2009). "A positive correlation was found between PLTP activity and Apo-A1 in plasma from patients with type 1 diabetes which is consistent with our observations." (PMID 19627602, 2009). "Thus, it seems that higher PLTP activity makes an important contribution to the higher apoA-I levels and altered HDL subclass distribution in type 1 diabetes." (PMID 24593955, 2014).
Alzheimer disease (3 papers, 2017 to 2023). A progressive, neurodegenerative disease characterized by loss of function and death of nerve cells in several areas of the brain leading to loss of cognitive function such as memory and language. "The similar strong upregulation (to 189%, P=0.08) of the phospholipid transfer protein (PLTP) transcript was assessed, because PLTP modifies ataxia, Alzheimer's disease and tau phosphorylation and serves as lipopolysaccharide interactor." (PMID 28108469, 2017). "PLTP functions are relevant for many pathophysiological alterations involved in neurodegenerative disorders (especially lipid metabolism, redox status, and immune reactions), and a significant increase in brain PLTP levels was observed in patients with Alzheimer's disease (AD) compared to controls." (PMID 29731975, 2018). "The female-biased genes in four regions were enriched for Alzheimer’s disease progression (SYN3 and STK32B) and the male-biased genes in four brain regions were enriched for neuroticism (PAX6 and PLTP)." (PMID 37221602, 2023).
COVID-19 (3 papers, 2021 to 2023). A disease caused by infection with severe acute respiratory syndrome coronavirus 2. "The lower PLTP activity we observed in COVID-19 patients is consistent with the lower proportion of extra-pulmonary organ dysfunction (septic shock, lactatemia, RRT and creatininemia) and the lower acute phase response (CRP levels)." (PMID 34031519, 2021). "PLTP (Phospholipid transfer protein), which could transport phospholipid metabolites, also showed an abnormal decline trend in COVID-19 patients." (PMID 35874944, 2022). "LDL cholesterol, HDL diameter and PLTP activity were independently associated with CRP concentration but not with COVID-19 status." (PMID 34031519, 2021). "In our case, an increase in PLTP and a decrease in LPL in COVID-19 samples were observed; however, the possible impacts on lipid composition are unknown." (PMID 37628421, 2023).
gastric cancer (3 papers, 2022 to 2023). A primary or metastatic malignant neoplasm involving the stomach. "The PLTP gene-encoding phospholipid transfer protein promotes proliferation of the gastric cancer cell and this gene expression (mRNA and protein) may be a marker of gastric cancer progression/prognosis." (PMID 36289879, 2022). "PLTP expression was found to be an appropriate marker for the course and prognosis of gastric cancer (GC)." (PMID 38022651, 2023).
Hypertension (3 papers, 2016 to 2025). The presence of chronic increased pressure in the systemic arterial system. "Many reports showed that CETP, LIPC and LIPG were associated with HDL and LDL and that MTHRR had known main effects for LDL and blood pressure, NR1I3 for lipid metabolism, PLTP for LDL, FOXO1 for LDL and hypertension, SMAD9 for hypertension, and CSMD1 for SBP." (PMID 27104857, 2016).
acute peritonitis (2 papers, 2021 to 2025). "In conclusion, HDLc and PLTP activity were associated with accelerated (increased H4) endotoxin elimination in patients with peritonitis, thus supporting the translation of the reverse lipopolysaccharide transport to human gram‐negative sepsis." (PMID 40682387, 2025). "In conclusion, using a model of peritonitis we demonstrated that PLTP promotes the binding of LPS to lipoproteins, making it a key factor of peritoneal clearance and neutralization." (PMID 34054798, 2021). "Our main finding is that, in a model of peritonitis, PLTP promotes the peritoneal clearance and neutralization of LPS, concurrently with binding of LPS to lipoproteins." (PMID 34054798, 2021). "PLTP promotes LPS peritoneal clearance and neutralization in a model of peritonitis." (PMID 34054798, 2021).
chronic obstructive pulmonary disease (2 papers, 2025). A chronic and progressive lung disorder characterized by the loss of elasticity of the bronchial tree and the air sacs, destruction of the air sacs wall, thickening of the bronchial wall, and mucous accumulation in the bronchial tree. "Increased expression of PLTP has been observed in the lung tissues of patients with chronic obstructive pulmonary disease (COPD)." (PMID 40182927, 2025). "PLTP expression is increased in chronic obstructive pulmonary disease through cleavage of PLTP by cathepsin G resulting in inflammation of the lung." (PMID 40822650, 2025).
Glucose intolerance (2 papers, 2022 to 2025). Glucose intolerance (GI) can be defined as dysglycemia that comprises both prediabetes and diabetes. "Nevertheless, studies have revealed that PLTP deficiency can worsen glucose intolerance and inflammatory conditions induced by a high-fat diet." (PMID 40444232, 2025). "Thus, PLTP deficiency exacerbates HF diet-mediated glucose intolerance." (PMID 36362012, 2022).
melanoma (2 papers, 2019 to 2021). A malignant, usually aggressive tumor composed of atypical, neoplastic melanocytes. "According to the analysis of human melanoma scRNA-seq, myeloid cells associated with responders showed a relatively high expression of PLTP, APOC1, APOE, MT1G, and MT1H." (PMID 34966676, 2021). "In concept, the increased expression of PLTP in the NM OMMs observed in the present study may be consistent with the production by the tumours of interleukin 6, which has been shown to inhibit melanoma growth." (PMID 31019223, 2019).
psoriasis (2 papers, 2022 to 2024). An autoimmune condition characterized by red, well-delineated plaques with silvery scales that are usually on the extensor surfaces and scalp. "This study discovers that increased CETP and PLTP aggravates psoriasis in an imiquimod-induced mouse model." (PMID 35982498, 2022). "Compared with other studies, the novelty of the present study is that both CETP and PLTP, the key proteins for lipid transfer and lipoprotein metabolism, affect pathological alterations in psoriasis." (PMID 35982498, 2022). "Elevated CETP and PLTP aggravate psoriasis in a imiquimod-induced mouse model." (PMID 35982498, 2022). "The present study demonstrated that elevated expression of CETP and PLTP could aggravate the clinical and pathohistological characteristics and inflammation in mice with psoriasis." (PMID 35982498, 2022). "This study examined whether elevated CETP and PLTP could aggravate psoriasis in a psoriasis vulgaris mouse model." (PMID 35982498, 2022). "Both are the best models for studying the relationship between lower HDL and psoriasis, so CETP-Tg and PLTP-Tg mice with low HDL were selected as the subjects." (PMID 35982498, 2022). "Therefore, whether CETP and PLTP affect psoriasis was observed in imiquimod-induced mouse models." (PMID 35982498, 2022).
rheumatoid arthritis (2 papers, 2018 to 2025). A chronic, systemic autoimmune disorder characterized by inflammation in the synovial membranes and articular surfaces. "PLTP was found to be highly abundant in the joints of rheumatoid arthritis (RA) patients and it was suggested it may directly trigger inflammation and fibroblast-like synoviocyte (FLS) proliferation, independent of its lipid transfer activity." (PMID 39968160, 2025).
steatosis (2 papers, 2023 to 2024). Increased lipid within the cytoplasm of cells. "p > 0.05), whereas GSE126848 showed statistically significant downregulation of PLTP in both steatosis and NASH (adj." (PMID 39562169, 2024). "Interestingly, an increase in expression of PLTP in steatosis or NASH was detected in two datasets, GSE48452 and GSE33814 (p < 0.05; adj." (PMID 39562169, 2024).
amyloid (1 paper, 2018). "In line with the present study, it would be worthwhile to determine the impact of PLTP overexpression in AD mice on amyloid deposition and cognitive functions." (PMID 29731975, 2018).
Anxiety (1 paper, 2018). Intense feelings of nervousness, tension, or panic often arise in response to interpersonal stresses. "Here we sought to determine whether dietary vitamin E supplementation can modulate neurotransmitter levels and alleviate the increased anxiety phenotype of PLTP-deficient (PLTP−/−) mice." (PMID 30618663, 2018). "In the present study, we sought to determine whether dietary vitamin E supplementation can modulate neurotransmitter levels and alleviate the increased anxiety phenotype of PLTP-deficient (PLTP−/–) mice." (PMID 30618663, 2018). "In the present study, and by our group, PLTP−/− mice were characterized by a 30% reduced cerebral vitamin E level and increased anxiety, as demonstrated using the Elevated Plus-Maze test." (PMID 30618663, 2018). "In contrast, “E” PLTP−/− mice displayed a normal anxiety level (60.3 ± 3.2% entries in closed arms compared to 63.1 ± 2.2% in WT mice)." (PMID 30618663, 2018). "In an earlier study, we observed that adult mice with a defect in the gene encoding plasma phospholipid transfer protein (PLTP) display a moderate reduction in cerebral vitamin E levels, and exacerbated anxiety despite normal locomotion and memory functions." (PMID 30618663, 2018). "To distinguish the impact of early vitamin E supplementation from that of late supplementation, we compared anxiety levels in “E” PLTP−/− mice, in “L” PLTP−/− mice, and in WT mice." (PMID 30618663, 2018).
aortic valve disease (1 paper, 2016). "Whereas the expression of PLTP (5.08 ± 0.15 vs. 2.77 ± 0.48, P = 0.006) in the left atria was significantly down-regulated in the patients with aortic valve disease and heart failure compared to normal controls." (PMID 27250500, 2016). "Notably, only ACADM, FABP3, ECH1, ACAA2, EHHADH, CPT1A and PLTP of the PPAR signaling pathway were differentially expressed in the left atria of MR patients compared to patients with aortic valve disease and normal controls." (PMID 27250500, 2016). "Notably, seven genes (ACADM, FABP3, ECH1, ACAA2, EHHADH, CPT1A and PLTP) of the PPAR signaling pathway were differentially expressed in the left atria of MR patients compared to patients with aortic valve disease and normal controls." (PMID 27250500, 2016). "Notably, only ACADM, FABP3, ECH1, ACAA2, EHHADH, CPT1A and PLTP of the PPAR pathway were significantly differentially expressed in the MR patients compared to patients with aortic valve disease and normal controls." (PMID 27250500, 2016). "However, MR patients with heart failure had significantly up-regulated PLTP expression in the left atria compared to patients with aortic valve disease and heart failure but had significantly down-regulated PLTP expression in the left atria compared to normal controls." (PMID 27250500, 2016).
Autoimmunity (1 paper, 2015). The occurrence of an immune reaction against the organism's own cells or tissues. "Since PLTP activity is linked to inflammation, autoimmunity, and the stability of the BBB, mechanisms affecting PLTP activity may provide new targets of research in MS." (PMID 26347820, 2015).
cholestasis (1 paper, 2004). Impairment of the bile flow caused by obstruction within the liver, or outside the liver in the bile duct system. "We propose that phospholipid transfer protein activity becomes reduced under cholestasis conditions because of changes in the chemical composition of high density lipoproteins, such as an increase in phospholipids content." (PMID 15543374, 2004).
coronary atherosclerosis (1 paper, 2022). Atherosclerosis of the coronary vasculature. "Among all the measured biochemical parameters (namely TG, TC, PL, HDL-C, LDL-C, apoA-I, PON-I, PLTP, and free glycerol), only the total PL serum and PON-I activity were significantly lower in patients with coronary atherosclerosis, which is in accordance with previous studies." (PMID 36312264, 2022).
Erythema (1 paper, 2022). Redness of the skin, caused by hyperemia of the capillaries in the lower layers of the skin. "Five consecutive days following the initiation of IMQ use, CETP-Tg and PLTP-Tg mice’s back skin displayed more signs of erythema, thickening, and scaling than WT mice." (PMID 35982498, 2022). "Consistent with a previous report, IMQ-induced psoriatic lesions, such as scaling, erythema, acanthosis, thickening, neoangiogenesis, and inflammatory infiltrates, appeared in WT mice and CETP-Tg and PLTP-Tg mice." (PMID 35982498, 2022).
gastric tumor (1 paper, 2020). "Using gastric tumor and adjacent normal tissue specimens collected in our hospital, we showed that MYO5A, PLTP, and TPP1 exhibited higher mRNA and protein expression in tumors than in normal tissue." (PMID 32735728, 2020).
heart failure (1 paper, 2016). Inability of the heart to pump blood at an adequate rate to meet tissue metabolic requirements. "Whereas the expression of PLTP (4.22 ± 0.14 vs. 2.77 ± 0.48, P = 0.006) in the left atria was significantly down-regulated in the MR patients with heart failure compared to normal controls." (PMID 27250500, 2016).
hyperlipidemia (1 paper, 2009). "Since there is an association between reduced HDL particle size and hyperlipidemia, it is possible that in our hyperlipidemic patient group there is a higher small HDL/large HDL ratio than in normolipidemic controls and this contributes to a negative correlation between PLTP activity and HDL." (PMID 19627602, 2009).
Hypocholesterolemia (1 paper, 2023). An decreased concentration of cholesterol in the blood. "Low serum PLTP activity in C3H-S mice with low Pltp expression was associated with hypertriglyceridemia, low serum TC or hypocholesterolemia, and low PL concentrations." (PMID 37620514, 2023).
IgA nephropathy (1 paper, 2023). "In IgA nephropathy, LYZL1 and SIPA1L3 risk genotypes are related to the decrease of Dialister and Bacilli and the risk genotypes of PLTP and AL365503.1 were associated with increased abundance of Erysipelotrichaceae and Lachnobacterium." (PMID 38189041, 2023).
ischemic stroke (1 paper, 2020). A stroke disorder caused by obstruction of blood flow to the brain, due to thrombotic (local blood clot formation) or embolic (due to a blood clot or other material traveling from another site) event. "The LPS-NC, LPS-binding protein (LBP), soluble CD14 (sCD14), lipoprotein profiles, apo(lipoprotein) A-I, apoB, and phospholipid transfer protein (PLTP) activity, were determined in 98 ischemic stroke patients and 100 age- and sex-matched controls." (PMID 32084157, 2020).
liver cirrhosis (1 paper, 2010). "Serum CETP, PLTP and LCAT activities in control subjects and patients with liver cirrhosis." (PMID 20470383, 2010).
liver diseases (1 paper, 2010). "Although reduced LCAT activity is common in a variety of liver diseases, the current report is, to the best of our knowledge, the first to identify increased CETP and PLTP activities as being associated with chronic liver impairment." (PMID 20470383, 2010).
lung disease (1 paper, 2018). "Deficiency of AAT could contribute to reduced lung PLTP activity and elevated neutrophil signaling associated with lung disease." (PMID 30337619, 2018). "Therefore, PLTP’s anti-inflammatory potential and signaling transduction in reducing inflammation associated with lung diseases require further investigations." (PMID 30337619, 2018).
Microscopic hematuria (1 paper, 2021). Microscopic hematuria detected by dipstick or microscopic examination of the urine. "Risk genotypes of PLTP rs6065904-AA/AG were associated with worse kidney function and more severe microscopic hematuria (MH)." (PMID 33436510, 2021).
multiple sclerosis (1 paper, 2015). A progressive autoimmune disorder affecting the central nervous system resulting in demyelination. "Further research is needed to elucidate the role of the phospholipid transfer protein in subjects with multiple sclerosis." (PMID 26347820, 2015).
osteoarthritis (1 paper, 2018). A noninflammatory degenerative joint disease occurring chiefly in older persons, characterized by degeneration of the articular cartilage, hypertrophy of bone at the margins and changes in the synovial membrane. "Lipid transfer activity of PLTP and pro-inflammatory cytokines were measured in sera and synovial fluid (SF) from RA patients and controls (healthy subjects or osteoarthritis patients [OA])." (PMID 29565987, 2018). "We also analyzed the level of PLTP activity in synovial fluids of patients with RA or other inflammatory rheumatisms (OIR) and osteoarthritis (OA)." (PMID 29565987, 2018).
periodontitis (1 paper, 2019). An acute or chronic inflammatory process that affects the tissues that surround and support the teeth. "Thus, the decreased levels of PLTP in the patient group suggest that PLTP is consumed during periodontitis, and a reduced reverse cholesterol transport has been suggested to occur in the disease." (PMID 30842338, 2019).